MMP14 (matrix metallopeptidase 14)
Diseases named in the same sentence as MMP14 in open-access papers (continued):
Sharing a sentence is not in itself a finding about the gene and the disease.
triple-negative breast carcinoma (13 papers, 2017 to 2025). An invasive breast carcinoma which is negative for expression of estrogen receptor (ER), progesterone receptor (PR), and human epidermal growth factor receptor 2 (HER2). "LIMK1 and LIMK2 were also shown to interact with the membrane-anchored type-1 matrix metalloproteinase (MT1-MMP, or MMP14) in triple-negative breast cancer." (PMID 36899941, 2023). "MMP-14 was also implied to contribute to poor response to chemotherapy in triple-negative breast cancer." (PMID 35586209, 2022). "The analysis using Kaplan-Meier plot revealed that MMP-14 expression in triple-negative breast cancer tissues was inversely correlated to therapeutical response when measured in relapse-free survival and overall survival." (PMID 35586209, 2022). "MMP-14 was found to be a valid target to control tumor progression and metastasis in triple negative breast cancer." (PMID 29983921, 2018). "In conclusion, we show that immunotherapies targeting MMP-14 can limit immune suppression, tumor progression, and metastasis in triple-negative breast cancer." (PMID 28938563, 2017). "MMP-14 located on the cell surface, is a potential target to stop metastasis and a novel antibody-mediated MMP-14 blockade seems to limit hypoxia and metastasis in triple negative breast cancer (TNBC) models." (PMID 29983921, 2018).
ovarian tumor (12 papers, 2008 to 2022). "Proteolytic activity by membrane type 1 matrix metalloproteinase (MT1-MMP, or MMP14) is required in part for the initial detachment of EOC cells from the primary ovarian tumor by cleaving α3-integrin on cancer cells and contributing to decreased cell adhesion." (PMID 34822024, 2022). "Further examination of the data suggested that alteration in gene expression of MMP-14 in ovarian tumors decreased the OS and PFS in patients compared to those who had unaltered MMP-14 gene." (PMID 35047406, 2021). "MMP-9 co-upregulation was also observed in our study, which is in agreement with the finding that MMP-9 (and MMP-14) mRNA levels are selectively increased in response to EGFR activity in ovarian tumor cells." (PMID 18211683, 2008). "Moreover, blockade of MMP-14 by a monoclonal antibody in MMP-14-expressing ovarian tumor cells, inhibited aggressive metastatic tumor development in a preclinical model." (PMID 24788523, 2014).
Alzheimer disease (11 papers, 2014 to 2025). A progressive, neurodegenerative disease characterized by loss of function and death of nerve cells in several areas of the brain leading to loss of cognitive function such as memory and language. "For example, MMP-14 can be mediate alteration of amyloid precursor proteolysis, a hallmark of Alzheimer's disease, in human neuronal cells." (PMID 35444067, 2022). "A recent study showed that the alteration of amyloid precursor proteolysis, a hallmark of Alzheimer's disease, was mediated by MMP-14 in human neuronal cells." (PMID 35444067, 2022). "In addition, elevated levels of MMP14 and aberrant MMP14 activity have been implicated in various age-related neurological conditions associated with cognitive impairment, such as Alzheimer’s disease and traumatic brain injury." (PMID 40983624, 2025). "MMP14 expression is upregulated in patients with neurodegenerative diseases such as Alzheimer’s disease, multiple sclerosis and stroke, as well as neuroinflammatory diseases." (PMID 31857661, 2019). "In patients with Alzheimer's disease (AD), MMP-14 was found overexpressed in brain, which was later corroborated by studies using a transgenic mouse model where MMP-14 was found in reactive astrocytes, in regions with fibrillar amyloid deposits." (PMID 28993312, 2017). "Similarly, elevated expression of MMP-14 has been detected in the brains of individuals with Alzheimer’s disease." (PMID 40983624, 2025). "Our findings support the potential of MMP14 as an Alzheimer's disease pharmacological target." (PMID 33282112, 2020). "Because MMP14 is upregulated in brain-infiltrating macrophages in Alzheimer disease, multiple sclerosis, and stroke, this promoter could be also used for gene therapy in noncancerous brain disorders accompanied by strong myeloid cell infiltration." (PMID 31501884, 2020). "Furthermore, increased levels of MMP-14 were also found in other amyloid-like neurodegenerative disorders such as Alzheimer's disease (AD)." (PMID 28993312, 2017).
diabetes (11 papers, 2017 to 2025). "High MMP-9 and MMP-14 levels are associated with rapid progression of diabetes which can be considered as prognostic factors." (PMID 35729613, 2022). "Second, depression, abdominal obesity, high MMP-14, and diabetes duration, were independently associated with CVD." (PMID 34702365, 2021). "In the MMP-14-labeled sample, examination of the periodontal tissue fragments from a diabetes mellitus patient revealed intensely positive immunoreactivity (+++) at the cell membrane level in the basal and parabasal layers membrane." (PMID 40075856, 2025). "In our personal research, the assessment of MMP-14 immunoreactivity revealed statistically significant differences in the intensity of membranous expression between diabetes patients and non-diabetes patients with periodontal pathology." (PMID 40075856, 2025). "A fragment of the gingival sulcus from a diabetes mellitus patient showed diffuse weakly positive (+) MMP-14 IR predominantly in the basal and spinous layers." (PMID 40075856, 2025). "The risk of diabetes incidence was found to increase in cases of high MMP-9 (β = − 5.853, p = 0.006) and high MMP-14 (β = − 31.613, p = 0.18)." (PMID 35729613, 2022). "In model 2, diabetes duration (AOR 1.13, p = 0.008), abdominal obesity (24.5, p = 0.004), depression (AOR 22.1, p = 0.006), and MMP-14 (per ng/mL) (AOR 1.01, p = 0.005), were associated with CVD." (PMID 34702365, 2021). "Numerous studies in the literature have shown that MMPs (such as MMP-2, MMP-7, MMP-8, MMP-9, MMP-14) register altered values in patients with DM (types 1 and 2) and this seems to contribute to several complications of diabetes." (PMID 34829612, 2021). "In model 3, diabetes duration (AOR 1.10, p = 0.012), abdominal obesity (15.8, p = 0.006), depression (AOR 17.4, p = 0.006), and high MMP-14 (AOR 14.2, p = 0.008), were associated with CVD." (PMID 34702365, 2021). "Depression (AOR 17.4, p = 0.006), abdominal obesity (15.8, p = 0.006), high MMP-14 (AOR 14.2, p = 0.008), and diabetes duration (AOR 1.10, p = 0.012) were associated with CVD." (PMID 34702365, 2021). "Contrary to MMP-9 and −13 upregulation, we detected downregulation of MMP-14 in diabetic kidney, which was ameliorated by GYY." (PMID 28883608, 2017). "The notable difference in membranous IR intensity between test and control groups suggests that both MMP-14 and CD 147 may play a role in the development of periodontal pathology for diabetes patients." (PMID 40075856, 2025). "We compared MMP-9 and MMP-14 levels in vitreous between diabetic and non-diabetic groups to analyze novel markers of diabetic retinopathy as diabetes is a risk factor of diabetic retinopathty." (PMID 35729613, 2022). "The risk of diabetes incidence increased with high levels of MMP-9 and MMP-14." (PMID 35729613, 2022). "Additionally, a correlation between MMP-3 and MMP-14 expression was observed, suggesting that MMP-3 might influence MMP-14 activity in the progression of periodontal disease linked to diabetes." (PMID 40075856, 2025). "Thus, overall results of MMPs expression obtained from our studies are in accordance with previous reports and strongly suggest that increased expression of MMPs-9 and 13, and decreased expression of MMP-14 were involved in the development of glomerulosclerosis in diabetes." (PMID 28883608, 2017). "The study found that CRP, MMP-2, MMP-14, TIMP-2, and IFN-γ contribute to the inflammatory processes driving periodontal damage in diabetes." (PMID 40075856, 2025). "A study by Ryu assessed how diabetes mellitus (DM) influences the expression of MMP-3 (stromelysin) and MMP-14 (membrane type) in the gingival tissues of patients with type 2 diabetes and healthy adults with chronic periodontitis." (PMID 40075856, 2025). "Spironolactone reduced this diabetes-induced increase in MMP mRNA, although this was only significant with MMP14." (PMID 36749631, 2023).
diabetes (continued). "When the correlation between diabetes duration and MMP-9 and MMP-14 levels was examined, it was observed that the level of these proteins increased significantly as the disease duration increased (p < 0.05)." (PMID 35729613, 2022). "The absence of cytoplasmic and nuclear expression of MMP-14 and CD 147 across all patients suggests that these markers are not active in these particular cellular compartments for both diabetes and non-diabetes patients with periodontitis." (PMID 40075856, 2025). "In addition to diabetes treatments, MMP-9 and MMP-14 inhibitors can be used to slow down the progression of diabetic retinopathy and to prevent retinal damage." (PMID 35729613, 2022). "Binary logistic regression analysis was performed to determine the risk factors of the presence of diabetes and the effect of MMP-9 and MMP-14 levels on being diabetic/nondiabetic group." (PMID 35729613, 2022). "The purpose of this study was to quantify and compare the expressions of MMP-14 and CD147 in gingival tissues of patients with and without type 2 diabetes mellitus." (PMID 40075856, 2025).
oral squamous cell carcinoma (11 papers, 2013 to 2025). "In our study, MMP-14 expression was relatively weak in premalignant lesions and markedly elevated in oral squamous cell carcinoma (OSCC)." (PMID 40572725, 2025). "In contrast, all 18 cases of oral squamous cell carcinoma (OSCC) showed strong positive (+++) MMP-14 expression in both the cytoplasm and membrane." (PMID 40572725, 2025).
rheumatoid arthritis (11 papers, 2006 to 2025). A chronic, systemic autoimmune disorder characterized by inflammation in the synovial membranes and articular surfaces. "Consistently, miR-150-5p is able to target MMP14 by binding to its 3′-UTR in fibroblast-like synoviocytes in the context of rheumatoid arthritis, thus causing downregulation of its expression." (PMID 36112264, 2023). "We have previously shown that sCD13, which is cleaved from its membrane-bound form by matrix metalloproteinase 14 (MMP14), activates endothelial cells (ECs), monocytes, and T cells, as well as rheumatoid arthritis (RA) fibroblast-like synoviocytes and dermal fibroblasts." (PMID 40168094, 2025). "The high expression of MMP‐14 in synovial tissue of RA (Rheumatoid arthritis) may promote synovial hyperplasia, pannus formation, and angiogenesis in RA progression." (PMID 30548828, 2019).
bladder cancer (10 papers, 2006 to 2025). "The MMP-14 activity determination in urinary bladder cancer tissue may be used as a predictor of a risk of metastasis." (PMID 32049862, 2020). "The tissues of low-grade urinary bladder cancer were characterized by a little reduction of the actual activity of MMP-14." (PMID 32049862, 2020). "Comparison of investigated enzymes’ activity and the inhibitor content suggests it opposite effects, higher suppression of MMP-14 than MMP-15 activity in low-grade bladder cancer and reverse TIMP-1 action in high-grade cancer." (PMID 32049862, 2020). "Comparison of investigated enzymes’ activity and the inhibitor content suggested it opposite effects, higher suppression of MMP-14 than MMP-15 activity in low-grade bladder cancer and reverse TIMP-1 action in high-grade cancer." (PMID 32049862, 2020). "S100A4 expression has proved to be a risk factor for muscle invasion in bladder cancer and found to increase the muscle invasion of bladder cancer in the early stages via MMP-14 expression." (PMID 29069865, 2017). "Urinary MMP-9 levels, serum MMP-7 levels, and tissue levels of MMP-2, MMP-7, and MMP-14 have been identified as prognostic markers of bladder cancer." (PMID 22852097, 2012). "The total content of MMP14 in bladder tissue depends on the stage of bladder cancer: it is reported at 10.133 ± 1.414 μg/mg protein for a low grade of the disease and 81.784 ± 9.876 μg/mg protein for a high grade, compared with 7.454 ± 1.183 μg/mg protein for control samples of bladder tissue." (PMID 41228251, 2025). "The calculated specific activity of MMP-14 was 2 times lower in low-grade urinary bladder cancer." (PMID 32049862, 2020). "MMP14 and MMP15, both belonging to the group of membrane-type proteinases, were compared as bladder cancer biomarkers." (PMID 41228251, 2025). "Several other MMPs are also considered as bladder cancer biomarkers: MMP1, MMP3, MMP7, MMP14, and MMP15." (PMID 41228251, 2025). "The level of MMP14 grows significantly with the grade of bladder cancer, while changes in MMP15 content in bladder cancer tissue, depending on the grade of the disease, are inconsistent." (PMID 41228251, 2025). "In bladder cancer, TAGLN can affect the upregulation of TGF-β-stimulated Slug and MMP14, and thus play a role in regulating EMT." (PMID 34552870, 2021). "The specific activity of investigated metalloproteinases was considerably higher for MMP-14 than for MMP-15, especially in the high-grade urinary bladder cancer." (PMID 32049862, 2020). "Moreover, MMP9, MMP12, MMP14, and MMP16-enriched KEGG pathways include “Bladder cancer, endocrine resistance, and relaxin signaling pathway” etc.." (PMID 39493455, 2024). "MMP14 and E-cadherin may be the downstream targets of HOXD10 and KLF4 in the miR-10b-mediated suppression of bladder cancer metastasis." (PMID 37627900, 2023). "MMP-14 dominates over MMP-15, particularly in high-grade urinary bladder cancer." (PMID 32049862, 2020). "Therefore, the inhibition of the miR-10b/HOXD10/MMP14 and miR-10b/KLF4/E-cadherin axes may offer potential therapeutic targets for metastatic bladder cancer." (PMID 37627900, 2023).
brain tumors (10 papers, 1999 to 2025). "We observed that in both U87 and U251 cell lines, silencing of MMP14 prolonged survival of mice with brain tumor xenografts (U87, P < 0.01; U251, P < 0.05)." (PMID 24156018, 2013). "Tumor cells themselves secrete active MMPs in exosomes (such as MMP-14,), and other brain tumor exosomes possess active MMPs (N Dusto and L Epple, unpublished)." (PMID 22848702, 2012). "Given its role in activating other MMPs and facilitating pericellular ECM degradation, MMP-14 is a key player in invasive brain tumors and may serve as a valuable marker for the prediction of brain tumor aggressiveness." (PMID 40265458, 2025). "MMP-14, a membrane-type MMP, is another enzyme with significant prognostic implications; its elevated levels are often associated with more invasive phenotypes, increased brain tumor grades, and poor prognoses." (PMID 40265458, 2025).
lymph node metastasis (10 papers, 2006 to 2025). "The present study demonstrated that both the expression of semaphorin-3A and MMP-14 in the observation group were closely associated with pleural invasion, lymph node metastasis, the number of metastatic lymph nodes, the degree of differentiation, vascular invasion and expression of PNCA." (PMID 24765144, 2014). "MMP-14 expression was positively correlated with all indicators of advanced disease, including lymph node metastasis (p = 0.0001), advanced stage (p = 0.0419), extrathyroidal extension (p = 0.0045), and increased risk of tumor recurrence (p = 0.0002)." (PMID 40869275, 2025). "We also found that survival was worse among patients with a high serum MMP-14, particularly among men, patients with pT3–4 tumors, in the presence of lymph-node metastases, or accompanying an intestinal cancer." (PMID 30532247, 2018). "In the NSCLC group, the positive rates of semaphorin-3A and MMP-14 expression were relevant to pleural invasion, lymph node metastasis, the number of metastatic lymph nodes, the degree of differentiation, vascular invasion and PCNA expression." (PMID 24765144, 2014). "Equally, elevated values of MMP-14 have been correlated with invasion, lymph node metastasis, and peritoneal dissemination." (PMID 24669030, 2014). "miR-34a plays an important role in lymph node metastases of TSCC through targeting MMP9 and MMP14 and may have potential applications in prognosis prediction and gene therapy for lymph node metastases of TSCC patients." (PMID 25268950, 2014). "Within this group of proteases, only MMP9, MMP13, MMP14, and TIMP1 have correlated with depth of tumoral invasion, lymph node metastasis, and an unfavorable prognosis in GC patients." (PMID 24669030, 2014). "In conclusion, our results demonstrated that miR-34a expression was significantly correlated with lymph node metastasis and prognosis of TSCC patients and could inhibit migration and invasion of TSCC cell lines via targeting MMP9 and MMP14." (PMID 25268950, 2014). "Binary logistic regression analysis showed that the expressions of circRNA-000121, hsa-miR-6775, hsa-miR-4763, MMP-14, and SRC in PTMC tissues were not significantly related to lymph node metastasis." (PMID 35891968, 2022).
mesothelioma (10 papers, 2000 to 2022). A usually malignant and aggressive neoplasm of the mesothelium which is often associated with exposure to asbestos. "The calculated relative risk of death in mesothelioma patients with low MMP14 expression was significantly lower than in patients with high MMP14 expression." (PMID 34572485, 2021). "This study investigated the influence of MMP2, MMP9, and MMP14 gene polymorphisms on time to progression and overall survival in mesothelioma patients." (PMID 29138529, 2017). "Different MMPs (MMP2, MMP9, MMP11, and MMP14) and their expression were studied in the mesothelioma tissue, but only a few have been prognostically significant." (PMID 29138529, 2017). "Most of these SNPs were located in regions reported to harbor aberrant alterations in mesothelioma (SLC7A14, THRB, CEBP350, ADAMTS2, ETV1, PVT1 and MMP14 genes), causing at most a 2–3-fold increase in MPM risk." (PMID 23626673, 2013). "In a cohort of 70 mesothelioma patients, we found by a multivariate Cox regression analysis, that the only parameter influencing overall survival was expression of MMP14." (PMID 19753302, 2009). "The most frequently investigated MMPs in mesothelioma are MMP2 (gelatinase A), MMP9 (gelatinase B), and MMP14." (PMID 34572485, 2021). "Keeping in mind the potential role of MMPs in mesothelioma and considering that only expression of MMP2, MMP9, and MMP14 has been studied in mesothelioma, we set out to perform a study exploring genetic variability of these genes." (PMID 29138529, 2017).